HLA-E (major histocompatibility complex, class I, E)
Diseases named in the same sentence as HLA-E in open-access papers (continued):
Sharing a sentence is not in itself a finding about the gene and the disease.
tumor (continued). "Because XPO1 is upregulated in tumors and selinexor selectively blocks translation in tumor cells, a potential advantage for blocking NKG2A:HLA-E interactions via selinexor rather than antibodies is that selinexor may retain expression of HLA-E on non-tumor cells." (PMID 34926302, 2021). "In addition to boosting NK cell cytotoxicity against targets expressing HLA-E, anti-NKG2A has also been demonstrated to augment the function of T cells expressing NKG2A, providing an opportunity to activate both NK and T cells; both were shown to contribute to control of tumor xenografts in mice." (PMID 31456796, 2019). "HLA-E, a non-classical major histocompatibility complex class I (MHC-I) protein, exhibits immunosuppressive properties, potentially influencing tumor immune evasion mechanisms." (PMID 40066089, 2025). "NKG2A, which binds the non-classical HLA molecule HLA-E, is expressed by subsets of natural killer (NK) cells, CD8+ T cells and innate T cells and negatively regulates their anti-tumour immune activity." (PMID 36560403, 2022). "Further, unlike HLA-E, which is expressed on almost all cell surfaces, NKG2A is mainly expressed in tumor lesions." (PMID 36032104, 2022). "Neither HLA-G1 nor HLA-E had any functional significance for the target-induced in vitro responses of CART against EwS cells, when artificially overexpressed on tumor cells." (PMID 34201079, 2021). "Another non-classical HLA molecule is HLA-E, which, like HLA-G, has immunosuppressive properties, and studies have found higher levels of HLA-E transcripts detected in all RCC cell lines and tumor lesions compared to standard renal epithelium." (PMID 33767709, 2021). "Optimal cancer-specific CTL function is determined by antigen sensitivity, which is influenced by TCR affinity to different tumor antigens peptide loaded onto MHC class Ia molecules and/or nonclassical MHC molecules such as HLA-E." (PMID 32451453, 2020). "This is particularly relevant in HCMV-infected tumours, where IFN-γ-rich environments may establish a negative feedback loop where immune activation induces checkpoint molecules (such as PD-L1 and HLA-E), which in turn suppress immune effector function." (PMID 41463341, 2025). "Likewise, the anti-NKG2A-mAb-IgG4 targets inhibitory NKG2A receptors on NK cells and disrupts their interaction with HLA-E (nonclassical MHC-I), strengthening NK-mediated anti-tumor responses." (PMID 38272918, 2024). "Notably, these include endogenous non-tumour ligands for the previously orphan immune checkpoint receptor VISTA, comprising the non-classical MHC molecules HLA-E and HLA-F." (PMID 35922511, 2022). "HLA-E overexpression was not correlated with any clinical prognostic factors such as FIGO (Chi2 test, p = 0.36), performance status (Chi2 test, p = 0.92), age (Wilcoxon test, p = 0.68), and residual tumor (Chi2 test, p = 0.75)." (PMID 35267497, 2022). "Previous studies have found that M2 macrophages with immunosuppressive properties can promote tumor immune escape by upregulation of non-classical MHC class I molecules (e.g., HLA-E and HLA-G), inhibitory ligands for T cells, apoptosis receptors (e.g., PD-L1, TRAIL, and B7-H4), and SIRP-alpha." (PMID 34717747, 2021). "Although GBM cells proper express low to negligent non-classical HLA-E, antigen presenting cells that constitute upto 50% of cells of the TME highly express HLA-E and may contribute to further tolerization of tumor infiltrating KIR-NKG2A+ NK cells." (PMID 25972872, 2015). "K562 tumor cells express ligands for receptors promoting natural cytotoxicity (Nectin-2/PVR for DNAM-1; MICA/B/UBLP1 for NKG2D), but do not express the 2B4 ligand CD48 or classical HLA-A, B, C, and non-classical HLA-E." (PMID 23508354, 2013).
tumor (continued). "For instance, introducing an sgRNA library into various tumor cells and categorizing them into in vitro cultures, immunodeficient NSG mice, wild-type mice, and ICB treatment groups, reveals that IFN-induced non-classical MHC class I molecules, Qa-1b/HLA-E, can impede ICB treatment." (PMID 39538305, 2024). "For instance, introducing an sgRNA library into various tumor cells and categorizing them into in vitro culture, immunodeficient NSG mice, wild-type mice, and ICB treatment groups, reveals that IFN-induced non-classical MHC class I molecules, Qa-1b/HLA-E, can impede ICB treatment." (PMID 39538305, 2024). "Notably, the non-classical HLA class I molecule HLA-E is expressed by various human malignancies (such as lung, colon, pancreas, stomach, head and neck, and liver tumors), and NKG2A+ NK cells can be found in the tumor nest." (PMID 36291830, 2022). "They analyzed GSC derived from primary tumor samples by mass cytometry, and the GSC expressed normal levels of NK cell activation receptor ligands (ULBP2, ULBP3, VIM) and upregulated levels of NK cell inhibitory receptor ligands (HLA-A, HLA-B, HLA-C, HLA-E, HLA-G, PCNA) compared with non-GSC." (PMID 34638384, 2021). "The current hypothesis is that optimal cancer-specific CTL function is determined by antigen sensitivity, which is influenced by T-cell receptor (TCR) affinity to different tumor antigens peptide loaded onto MHC class Ia molecules and/or nonclassical MHC class Ib molecules, such as HLA-E." (PMID 32451453, 2020).
cancer (150 papers, 2011 to 2026). A tumor composed of atypical neoplastic, often pleomorphic cells that invade other tissues. "In microsatellite instable (MSI) cancer, HLA-E/B2M are aberrantly overexpressed and are associated with NKG2A-expressing CD94+ T cells and NK cells." (PMID 38041084, 2023). "In the case of cancer, for example, the precise identification of neoepitopes derived from DNA mutations and recognized by specific HLA-E-restricted T lymphocytes would allow their use as targets in the development of new immunotherapies." (PMID 34446788, 2021). "HLA-E can inhibit NK cells and T cells and has been shown to induce regulatory T cells and as a result expression of HLA-E in tissues has been associated with immune suppression in pregnancy and cancer and with viral immune-escape." (PMID 34295330, 2021). "In this way, high expression of HLA-E or exhausted NKG2A+ve NK cells are associated with poor prognosis in different cancers." (PMID 33304346, 2020). "Probably this can be linked to a repertoire of peptides associated with HLA-E protein and its lower inhibitory effect on cytotoxic lymphocytes as, for example, in the case of cancer diseases." (PMID 31690066, 2019). "We can suggest that high surface level of HLA-E on cancer cells makes the differences between both alleles negligible in these diseases." (PMID 31690066, 2019). "Our results showing that high-risk HPV E7 downregulates HLA-E expression imply dual roles of HLA-E that induces antiviral immunity in normal cells but suppresses antitumor immunity in cancer cells." (PMID 28623356, 2017). "Notably, HLA-E overexpression in cancers has also been associated with poor prognosis in GBM, gastric cancer, and multiple myeloma." (PMID 41463341, 2025). "Specifically, further research is needed to ascertain whether the alterations in HLA-E, B2M, and HLA-B, as indicated in our findings, are indeed linked to cancer immune evasion through the loss of MHC Class I antigen presentation." (PMID 38256174, 2024). "The human leukocyte antigene E (HLA-E) is associated with tumorigenesis in various cancers." (PMID 38069020, 2023). "Overexpression of HLA-E is observed in several cancers and linked to poor outcome." (PMID 33671917, 2021). "Accordingly, it has been speculated that the high levels of HLA-E may inhibit NK cell activation caused by downregulation of classical MHC-I expression on cancer cells." (PMID 28623356, 2017). "HLA-E's function as an immune checkpoint in cancer depends on its display of the canonical peptide (VL9), yet direct profiling of these complexes has been stymied by lack of specific reagents." (PMID 42080134, 2026). "Disruption of the NKG2A:HLA-E immune checkpoint axis to enhance NK or CTL activation against cancer is a hotspot of immunotherapy." (PMID 40634299, 2025). "-Some preclinical studies have already shown that blocking HLA-E through antibodies or downregulating HLA-E expression through the approved anti-cancer drugs selinexor and bortezomib enhance NK cell cytotoxic activity in solid tumor." (PMID 40433358, 2025). "Correlation analysis showed a strong association between CDKN1C, a key senescence marker, and HLA-E expression in HLA-E positive cancer cells (R > 0.5, p < 0.05)." (PMID 40959273, 2025). "Consistent with previous findings, CellChat analysis indicated that HLA-E-positive cancer cells can regulate NK cell function through the binding of inhibitory receptors CD94/NKG2E via HLA-E in all subsets of NK cells (CD56+CD16−, CD56+CD16+, and CD56−CD16+)." (PMID 40959273, 2025). "HLA-E, often overexpressed on cancer cells, binds to the inhibitory receptor NKG2A, leading to functional depletion and reduced cytotoxicity of NKs." (PMID 40211394, 2025). "In the progression of malignant tumors, cancerous cells often upregulate HLA-E expression as a mechanism to circumvent immune surveillance." (PMID 41315184, 2025).
cancer (continued). "In terms of both the number and weight score of cell-cell interactions, cancer cells, particularly HLA-E-positive cancer cells, played a crucial role in shaping the pleural microenvironment, while mesothelial cells played a secondary role." (PMID 40959273, 2025). "Across the six studies included in our DFS analysis, a common theme emerged: HLA-E expression was linked to worse DFS outcomes, despite the variability in cancer types and methodologies." (PMID 40066089, 2025). "Generally, HLA-E has low cell surface expression, but certain pathogens and cancer cells can upregulate its expression." (PMID 41463341, 2025). "Gene Set Enrichment Analysis (GSEA) further supported that HLA-E positive cancer cells exhibited a senescence phenotype." (PMID 40959273, 2025). "Our findings indicated that HLA-E-positive cancer cells, mesothelial cells, and aDC2 regulate MAIT cells through the BAG6-NCR3 axis, with high BAG6 concentrations correlating with worse patient prognosis." (PMID 40959273, 2025). "This aptamer activated T cells by impeding the CTLA-4 interaction with B7-1/B7-2, enhancing the eradication of cancer cells, and augmenting NK cells’ capacity for detecting and eliminating HLA-E-expressing cancer cells by inhibiting NKG2A." (PMID 38473398, 2024). "The high-affinity activation of CD16a receptors is crucial in cancer immunotherapy because it not only activates resting NK cells, but also helps them overcome inhibitory signals from HLA-E, which is often overexpressed on cancer cells." (PMID 39911822, 2024). "NKG2A binds human leukocyte antigen (HLA)-E, and upregulation of HLA-E on cancer cells can inhibit both CD8+ T cell and NK-cell function via NKG2A." (PMID 38223411, 2024). "The HLA-E/NKG2A immune checkpoint axis holds potential as a next-generation immunotherapeutic strategy for cancer." (PMID 39584993, 2024). "The downregulation of TAP leads to an expansion of the HLA-E immunopeptidome, suggesting a plausible avenue for anti-cancer treatments centered around targeting TAP-independent HLA-E epitopes." (PMID 39301027, 2024). "When expressed on the surfaces of cancer cells, HLA-E has been shown to mediate inhibitory signals to NK cells via interactions with the NKG2A receptor." (PMID 39329751, 2024). "By exploring the specific functions of HLA-E, HLA-F, HLA-G, and HLA-H in various cancers, the authors aim to highlight their importance in the immune system’s interaction with tumors." (PMID 39766165, 2024). "Understanding the broad repertoire of actionable peptides presented by HLA-E can lead to innovative treatments for viral and pathogen infections and cancer, leveraging its monomorphic nature for broad therapeutic efficacy." (PMID 39301027, 2024). "Our analysis showed a decreased expression of HLA-E in individuals with cancer, demonstrating an inhibited immune response." (PMID 39672307, 2024). "This suggested that upregulation of MHC‐I and HLA‐E was driving NK cell inhibition, which has been shown previously in other cancer types as providing a means of escape from NK surveillance." (PMID 38435825, 2024). "Their data indicate that T cell responses to TAAs were comparable to viral antigen-specific responses and, therefore, suggest that the HLA-E immunopeptidome can be exploited for CD8+ T cell-based immunotherapies against cancer." (PMID 39301027, 2024). "In cancers, classical HLA class I molecules are lost to prevent T-cell-mediated recognition but, interestingly, the expression of HLA-E molecules is enhanced." (PMID 36829496, 2023). "Given HLA-E’s role in cancer immune escape, it appears as a good candidate to implement the immune checkpoint inhibitory strategy." (PMID 36829496, 2023). "The upregulation of HLA-Ib in cancer cells is primarily based on very extensive documentation of HLA-E." (PMID 37627243, 2023).
cancer (continued). "HLA-C and HLA-E are broadly expressed on healthy tissues to define immune “self”, but HLA-E can be over-expressed on cancer cells or HIV-1 infected T lymphocytes to escape immune recognition." (PMID 37936122, 2023). "The most promising anti-NKG2A mAb, called monalizumab, prevents the interaction between NKG2A and HLA-E and exhibits a potent therapeutic impact on several cancer types, such as NSCLC, CRC, and SCCHN." (PMID 38041084, 2023). "Given the known impacts of HLA-E expression on cancer development, it is likely that these are exacerbated by NKG2A expression on NK cells in other cancer types, though this remains to be studied extensively." (PMID 38090565, 2023). "As part of its cancer immunoactivity, selenite inhibited the human leukocyte antigen E (HLA-E) protein on the membranes of cancer cells to activate natural killer (NK) cell anticancer immunity." (PMID 36986636, 2023). "Many HLA molecules, for example, HLA-E, HLA-F, HLA-G, HLA-H and HLA-DR were reported to be overexpressed on cancer cells." (PMID 36778644, 2023). "Because HLA-E expression increases following various cellular stresses, including cancer-related inflammation, it is probable that HLA-E/NKG2C binding is likely to strongly influence the immune response to eliminate infected cells." (PMID 37371767, 2023). "In xenografted mice bearing HLA‐E‐expressing human cancer cells, intratumoral co‐injection of activated allogeneic human NK cells and clinical‐grade anti‐NKG2A mAb (monalizumab) synergistically achieved therapeutic effects." (PMID 37782273, 2023). "Several groups have observed a significant enhancement in the antitumor effects of immune checkpoint blockade (ICB) and cancer vaccines when combined with HLA-E/NKG2A axis blockade." (PMID 38052854, 2023). "We found that cancer cells with higher levels of CNV displayed lower levels of MHC-I genes (HLA-A, HLA-B and HLA-E) and the B2M gene, suggesting that these cancer cells were less immunogenic." (PMID 36596773, 2023). "Both CD8+ T cells and NK cells have the inhibitory receptor CD94/NKG2A that combines with the HLA-E on the cancer cell." (PMID 38041084, 2023). "The NKG2A:HLA-E checkpoint is a highly promising and novel immune checkpoint target for the treatment of cancer." (PMID 36560403, 2022). "HLA-E expression can be increased on cancer cells by the presence of pro-inflammatory cytokines such as IFNγ that confer protection from NK cell lysis, demonstrating an immune escape mechanism in a pro-inflammatory environment." (PMID 36560403, 2022). "This opens perspectives for treatment of certain cancers or in allogeneic transplantation of B2M-negative pluripotent stem cells expressing a single-chain HLA-E trimer." (PMID 36518759, 2022). "As a heterodimer NKG2A/CD94, it binds to HLA-E and transduces inhibitory signals, its blockade was therefore considered in cancer treatment." (PMID 35392095, 2022). "Such monospecific anti-HLA-E mAb is highly valuable for immunodiagnosis of HLA-E on human cancers which are known to upregulate HLA-E gene expression correlated with overexpression of cell-surface HLA-E." (PMID 36134954, 2022). "The NPS was significantly and positively associated with HLA genes, including TAP1, HLA-E, HLA-DRA, B2M, TAP2, HLA-DPA1, and HLA-DOA in all cancers." (PMID 36170029, 2022). "The crucial role of NKG2A and HLA-E in dampening immune effector activation against cancer has made this inhibitory axis a key target for immunotherapeutic strategies." (PMID 36560403, 2022). "In the contrary, we uncovered a negative association between METTL1 expression and HLA-DOA as well as HLA-E among nearly all cancers." (PMID 35432338, 2022). "HLA-E gene expression in some cancers (e.g., melanoma) is ranked 19th among the most overexpressed genes." (PMID 36134954, 2022).